MSH6 (mutS homolog 6)
Diseases named in the same sentence as MSH6 in open-access papers (continued):
Sharing a sentence is not in itself a finding about the gene and the disease.
tumor (continued). "Substantial CNV deletions were observed in PABPC5, MSH6, IFI16, GNS, ERCC4, BRCA1 and ACACB, while substantial CNV amplification was observed in most tumour types for the remaining genes." (PMID 37660060, 2023).
tumor (continued). "At the same tumor, 4 cases were abnormal both for MLH1 and PMS2 and one case was abnormal for both MLH1 and MSH6." (PMID 34306129, 2021). "The genes involved in tumor suppression (e.g., TGFBR2), cell proliferation, DNA repair (e.g., MSH3 and MSH6), apoptosis (e.g., BAX), etc., contain repetitive sequences in the coding regions, and alterations tend to develop in these regions." (PMID 34185173, 2021). "Tumor analysis of the tumor of one of the digenic carriers and the in vitro MMR activity assay indicated retention of MMR function of MSH6 p.Thr1100Met protein." (PMID 32615015, 2020).
tumor (continued). "Adding tumour location also improved the performance of PREMM5 for identifying MLH1 (AUC 0.92 [95% CI 0.88–0.97] vs. 0.80 [95% CI 0.71–0.89]) and MSH6 (AUC 0.75 [95% CI 0.65–0.84] vs. 0.69 [95% CI 0.58–0.80]) mutation carriers." (PMID 28933000, 2018). "Surgical tumor samples were histopathologically analyzed for immunoexpression of MGMT, MSH6 and MIB-1." (PMID 28900805, 2017). "The results obtained in our study in combination with published reports support that MSH6 and RUNX1T1 have oncogenic and tumor suppressive functions respectively in cancers." (PMID 29046615, 2017). "MSI was examined for 35/43 (81%) paired blood and tumor-derived DNA samples, including those with increased MLH1 and MSH6 methylation, using five microsatellite markers: NR-21, NR-24, BAT-25, BAT-26, and MONO-27." (PMID 27902704, 2016).
tumor (continued). "Unsupervised hierarchical cluster based on relative quantification of the 5 E2F-induced genes, CCNA2, CCNB1, CCNB2, MSH6 and MCM7, by RT–qPCR divided the 24 tumours into two groups." (PMID 22045185, 2011). "Besides the nine different MSH6 germline mutations found in patients with an MSI-high tumour, two pathogenic mutations in MSH6 were found in patients in whom MSI analysis could not be performed." (PMID 17117178, 2006). "PMS2 and MSH6 were scored manually as “lost” or “present”, without estimating the percentage of negative tumour cells." (PMID 39040241, 2024). "Similar to G411 xenograft tumors, pronounced CD44 expression is present in G361 MSH6−/− tumor cells but not nontumoral cells." (PMID 36989359, 2023).
tumor (continued). "While clinical data were equivocal with respect to the pathogenicity of MSH6, in part due to the lack of availability of historic tumor specimens, the functional data provide evidence for the MSH6 c.3936_4001+8dup variant being pathogenic." (PMID 36612224, 2022). "In contrast, absence of MSH6 expression was observed in both tumor cells and the surrounding normal tissue." (PMID 33924881, 2021). "Baseline genomic alterations in circulating tumor DNA, including SMARCA2, MSH6, APC signaling pathway, and Wnt signaling pathway, might be associated with the risk of HPD." (PMID 34858840, 2021). "The characteristic pattern of expression seen in CMMRD, namely lack of nuclear expression in both the tumor and the normal cells with MSH6 protein, was crucial." (PMID 33924881, 2021). "No somatic alterations in FBXO11, MSH6 or BCL6 were present, nor did we find hypermutation in the tumor or a mutational signature related to MMR deficiency." (PMID 33811277, 2021).